IL31RA (interleukin 31 receptor A)
Description:
Functions as a membrane-bound signal-transducing subunit of the IL31 receptor complex (heterodimer composed of OSMR and IL31RA) which binds IL31. Functionally, IL31 signaling via OSMR/IL31RA is particularly important in skin immunity. Mechanistically, ligand binding induces heterodimerization with OSMR, activating JAK1 and JAK2 (and to a lesser extent TYK2) associated with the intracellular domains of IL31RA and OSMR. These kinases phosphorylate tyrosine residues on IL31RA and OSMR, creating docking sites for STAT1, STAT3, and STAT5B, which are then phosphorylated and activated (Probable). In addition, the IL31 receptor complex activates the MAPK pathway (MAPK3/ERK1-MAPK1/ERK2) via recruitment of the adapter protein SHC1. Mediates IL31-induced itch, probably in a manner dependent on cation channels TRPA1 and TRPV1 (By similarity). Positively regulates numbers and cycling status of immature subsets of myeloid progenitor cells in bone marrow in vivo and enhances myeloid progenitor cell survival in vitro (By similarity).
Synonyms: IL-31RA; GLM-R; hGLM-R; GPL; CRL3; CRL; Glmr; PLCA2; PRO21384; zcytoR17
Tractability: Antibody: a drug acting on it is in phase 2 or 3 trials; UniProt places it where antibodies can reach, with high confidence; its Gene Ontology location is reachable by antibodies, with high confidence; UniProt predicts a signal peptide or a membrane-spanning region; the Human Protein Atlas places it where antibodies can reach.
Target class: Membrane receptor
Gene: Protein-coding gene on chromosome 5 (55,851,357 to 55,922,854, forward strand). Ensembl gene ENSG00000164509.
Subcellular location: Cell membrane; Presynaptic cell membrane; Cell projection, axon
Subcellular location (Human Protein Atlas): Cytosol; Plasma membrane
Pathways (Reactome):
Immune System: IL-6-type cytokine receptor ligand interactions
Gene Ontology:
Molecular function: cytokine receptor activity; cytokine binding; protein kinase binding; transcription coactivator activity
Biological process: cell surface receptor signaling pathway via JAK-STAT; cytokine-mediated signaling pathway; monocyte differentiation; positive regulation of cell population proliferation; positive regulation of tyrosine phosphorylation of STAT protein; cell surface receptor protein tyrosine kinase signaling pathway; defense response; homeostatic process; macrophage differentiation; MAPK cascade; negative regulation of apoptotic process; negative regulation of macrophage activation; positive regulation of DNA-templated transcription; cell differentiation
Cellular component: external side of plasma membrane; membrane; plasma membrane; receptor complex; axon; presynaptic membrane
Genetic constraint (gnomAD): Loss-of-function variants: 50 observed, 66.55 expected, observed/expected ratio (o/e) 0.75, 90% interval 0.6 to 0.95. The upper end of that interval is the gene's LOEUF score, 0.95, which puts it in group 4 of 6, group 1 being the genes least tolerant of losing a copy. Missense variants: 716 observed, 867.32 expected, observed/expected ratio (o/e) 0.83, 90% interval 0.78 to 0.88. Synonymous variants: 301 observed, 317.8 expected, observed/expected ratio (o/e) 0.95, 90% interval 0.86 to 1.04.
Homologues: Orthologues: chimpanzee IL31RA (99% identical), macaque IL31RA (93% identical), pig IL31RA (69% identical), dog IL31RA (66% identical), rabbit IL31RA (63% identical), guinea pig IL31RA (61% identical), mouse Il31ra (57% identical), rat Il31ra (56% identical). Paralogues in human: IL6ST (24% identical), CSF3R (18% identical), IL12RB2 (16% identical), LIFR (16% identical), OSMR (15% identical), LEPR (14% identical), IL12RB1 (14% identical), IL27RA (12% identical), IL23R (11% identical), CRLF1 (11% identical), PRLR (10% identical), GHR (9% identical), and 11 more.
Diseases named in the same sentence as IL31RA in open-access papers:
IL31RA is named in the same sentence as 54 diseases in open-access papers, as found by Europe PMC text mining. Sharing a sentence is not in itself a finding about the gene and the disease. The quoted sentences say what the papers report.
Pruritus (16 papers, 2019 to 2025). Pruritus is an itch or a sensation that makes a person want to scratch. "In fact, the humanized anti-IL31RA nemolizumab was recently approved in Japan for the relief of AD-associated pruritus." (PMID 38035099, 2023). "More recent findings have demonstrated that nemolizumab, an anti-IL-31RA antibody that binds to IL-31RA with subsequent inhibition of IL-31 signaling effectively relieves AD-associated pruritus." (PMID 33681256, 2021). "In a phase 2 trial, a humanized monoclonal anti-IL-31Rα antibody significantly improved pruritus in AD patients." (PMID 39962262, 2025). "Targeting the IL-31/IL-33 axis represents an emerging therapeutic option, e.g., nemolizumab (anti-IL-31RA) significantly reduces pruritus and AD symptoms in clinical trials." (PMID 41155460, 2025). "Nemolizumab is a humanized monoclonal antibody that targets the interleukin-31 receptor A (IL-31RA), thereby blocking IL-31-mediated pruritus signaling pathways." (PMID 41464561, 2025). "Although little research has been done on IL-31 production in CNS, IL-31 receptors (IL-31RA and OSMR β) have been extensively found in the brain tissues and spinal cord and IL-31 is acknowledged as causing pruritus in AD." (PMID 40443235, 2025). "In PN lesions, this receptor is also notably increased, and the intensity of pruritus in PN is closely related to the number of IL-31+ cells and IL-31Rα+ cells in the dermis." (PMID 38077377, 2023). "IL-31 induces the expression of TRPV1 and Interleukin 31 Receptor A (IL-31RA) in neurons through the Jak1-Stat3 pathway, thereby increasing the sensitivity of itch sensory neurons." (PMID 35646918, 2022). "The number of IL-31RA+ or OSMRβ+ cells is also correlated with pruritus intensity in patients with bullous pemphigoid." (PMID 33924978, 2021). "In this condition, the intensity of pruritus is correlated with the numbers of dermal IL-31+ cells and dermal IL-31RA+ cells." (PMID 33924978, 2021). "These MrgprC11+ sensory nerve fibers mostly coexpress IL-31 receptor (IL-31RA/OSMRβ), which signals IL-31-induced pruritus to DRG neurons, the spinal cord, the hypothalamic tract and finally to the brain." (PMID 33924978, 2021). "Although IL-31/IL-31RA interaction has been identified as one of the key determinants of pruritus in AD, there are limited reports regarding the effect of IL-31/IL-31RA interaction on Th2-deviated immune conditions in AD." (PMID 31434203, 2019). "Similarly, IL-31 released by type 2 immune cells in skin lesions mediates pruritus by stimulating neurons expressing IL-31 receptor subunit α (IL-31Rα), increasing neurite branching in the skin." (PMID 39962262, 2025). "We speculate that OSM may suppress IL-31-induced pruritus by reducing IL31RA expression and downstream ERK activity in both DRGs and keratinocytes." (PMID 38035099, 2023). "In addition to mediating the sensation of pruritus, IL-31 promotes nerve fiber elongation and the branching of murine small-diameter DRG neurons, which is abrogated in DRG neurons from Il31ra-deficient mice." (PMID 33924978, 2021). "The mechanism behind this is still not fully understood, but it has been shown that IL-31RA is expressed on sensory neurons and IL-31 derived from activated T cells under Th2-skewed conditions stimulates IL-31RA on sensory nerves, resulting in severe pruritus in AD." (PMID 31434203, 2019). "Based on the available literature, eosinophils, IgG autoantibodies, IgE autoantibodies, SP and its receptor NK1R, IL-31 and its receptor OSMRb, IL-31RA, IL-13, IL-4, periostin, and basophils may be responsible for pruritus in BP and could be potential therapeutic targets." (PMID 39459488, 2024). "Moreover, Il31ra-deficient mice do not develop pruritus and dermatitis in response to mouse IL-31, and the administration of an anti-mouse IL-31 antibody ameliorates the scratching behavior in NC/Nga mice with atopic dermatitis-like skin lesions." (PMID 33924978, 2021).
Pruritus (continued). "Mechanistically, activation of IL-31RA has been shown to sensitize TRPV1 and TRPA1 ion channels for pruritus." (PMID 36520531, 2023). "The number of the IL‐31 positive cells in the dermis did not correlate with pruritus severity;39 however, protein levels of IL‐31 receptors, IL‐31RA and OSMR, in both epidermis and dermis, were increased and correlated with pruritus severity." (PMID 36477831, 2023). "IL-31/IL-31RA interaction activates signal transduction pathways leading to expression and release of various chemokines, proinflammatory cytokines, regulation of cell proliferation and stimulation of DRG neurons that play important role in pruritus induction and inflammatory diseases." (PMID 33681256, 2021).
atopic dermatitis (10 papers, 2017 to 2025). "Nemolizumab, an IL-31Rα human monoclonal antibody, is approved for atopic dermatitis (AD) and prurigo nodularis." (PMID 40661111, 2025). "The efficacy of anti-IL-31RA (nemolizumab) treatment has been demonstrated for the treatment of itch in atopic dermatitis and chronic prurigo." (PMID 35893400, 2022). "Recently, CIMM331 humanized anti-human IL31RA antibody was tested in a phase I/Ib study for patients of atopic dermatitis." (PMID 32528891, 2020). "Treatment of mice that developed atopic dermatitis-like skin inflammation with anti-IL-31 or anti-IL-31RA neutralizing Ab resulted in attenuation of scratching behavior, but not the severity of skin inflammation." (PMID 29703903, 2018). "If this stimulation continues for a long time, it may become atopic dermatitis due to the overexpression of DRG neuronal IL-31RA." (PMID 37511321, 2023). "The heterodimeric receptor consisting of IL31ra and Osmr has been reported to mediate itch evoked by interleukin-31 (IL31), which is involved in atopic dermatitis." (PMID 28701920, 2017).
allergic asthma (5 papers, 2019 to 2023). A asthma with a basis in a pathological type I hypersensitivity reaction. "To further establish the role of IL-31RA in allergic asthma, we used an alternative mouse model of SEA-induced allergic asthma." (PMID 38081868, 2023). "We hypothesized that in a house dust mite (HDM)-induced model of allergic asthma, the loss of IL-31RA would block the development of some, if not all, pathological features of allergic asthma." (PMID 38081868, 2023). "However, the role of IL-31RA in the development of Th2 responses during allergic asthma remains unclear." (PMID 38081868, 2023). "Together, these results suggest an important role for IL-31RA in the regulation of AHR, and identifying the molecular events underlying IL-31RA-driven AHR may lead to the development of therapeutic approaches against AHR in allergic asthma." (PMID 38081868, 2023). "Here, we provide evidence that both Th1 and Th2 cytokines (IFNγ, IL-4, and IL-13) upregulate IL-31RA but not IL-31 in SMC and lungs during allergic asthma." (PMID 38081868, 2023).
breast carcinoma (5 papers, 2017 to 2022). "Next, focusing on data from the entire cohort of patients with breast cancer, we found that high coexpression of IL-31Ra, IL-4, IL-2, and Granzyme B was associated with increased survival, with results almost reaching statistical significance (p=0.056)." (PMID 32843492, 2020). "Our results show that the expression level of IL31RA is up-regulated in BLBC in comparison with other breast cancer subtypes." (PMID 32528891, 2020). "Overexpression of IL31RA in luminal breast cancer cells enhances the cancer stem cell-like properties and cell motility." (PMID 32528891, 2020). "Three datasets from Gene expression omnibus (GEO) that contain gene expression information of breast cancer patients were analyzed; the data indicated that the mRNA level of IL31RA is positively correlated to that of Twist in breast cancer." (PMID 32528891, 2020). "Next, we sought to investigate the expression status of IL31RA in breast cancer." (PMID 32528891, 2020). "Interestingly, IL31RA was observed to have highest expression level in BLBC compared with other subtypes of breast cancer." (PMID 32528891, 2020). "However, the functional roles of IL-31/IL31RA signaling in basal-like breast cancer (BLBC) progression remain totally unclear." (PMID 32528891, 2020). "All these data indicate that IL31RA is required for breast cancer cell invasion and metastasis." (PMID 32528891, 2020). "Interestingly, data from a study of patients with breast cancer demonstrate that there is a significant extended survival to breast cancer patients with a higher level expression of IL31RA." (PMID 29484036, 2018). "To verify the biological roles of IL31RA in breast cancer, we constructed IL31RA stable over-expression clone in MCF-7 luminal breast cancer cells by transfection of lentivirus-based expression plasmid." (PMID 32528891, 2020).
dermatitis (5 papers, 2015 to 2024). An inflammatory process affecting the skin. "Mite infestation and IL-31 administration triggered itchy skin, increased LLS counts and DRG neuronal IL-31RA expression, and eventually caused dermatitis." (PMID 36674561, 2023). "Further, the relationship between itching and the expression of neuronal DRG IL-31RA mRNAs in NC/Nga, BALB/c, and C57BL/6 mice was analyzed, and the regulatory mechanisms underlying dermatitis development were elucidated." (PMID 36674561, 2023). "IL-31 and DRG neuronal IL-31RA are important factors inducing itching and promoting scratching and dermatitis." (PMID 36674561, 2023). "These monocytes may play a role in IL‐31‐mediated neuroimmune pathways and could be involved in paradoxical dermatitis flare‐ups in AD patients undergoing anti‐IL31RA therapy." (PMID 39654684, 2024). "It acts via a heterodimeric receptor composed of IL-31Rα and oncostatin M receptor β and expression of IL-31 correlates with the expression of IL-4 and IL-13 suggesting that IL-31 is involved in Th2-mediated skin inflammation." (PMID 25756056, 2015). "IL-31 and its receptors IL-31RA and OSMR are involved in AD, pruritus, and dermatitis at the mRNA level." (PMID 36674561, 2023). "In conclusion, neuronal IL-31RA expression in the DRG was the most important genetic factor affecting the severity of LLS and dermatitis in mice." (PMID 36674561, 2023).
autoimmune disease (3 papers, 2017 to 2021). A disorder resulting from loss of function or tissue destruction of an organ or multiple organs, arising from humoral or cellular immune responses of the individual to their own tissue constituents. "STAT1 related regulation of IL-31RA may link this pathway also with autoimmune diseases such as systemic sclerosis, dermatomyositis and lupus erythematosus." (PMID 33644104, 2021). "The established studies suggested that soluble IL-31RA might expand the range of responsive cells and tissues because of the transsignaling for IL-6; meanwhile, myocarditis had overlapping loci with diabetes and SLE, suggesting that these autoimmune diseases shared genetic traits." (PMID 28572699, 2017).
neuroblastoma (3 papers, 2016 to 2024). Neuroblastoma (NB) is the most common solid, extracranial childhood tumor. "Later on, the same group reported that common variants in BARD1 gene were associated with high-risk neuroblastoma, and polymorphisms within DUSP12, DDX4, IL31RA, and HSD17B12 were associated with low-risk neuroblastoma." (PMID 31341530, 2019).
pulmonary fibrosis (3 papers, 2021 to 2023). Chronic progressive interstitial lung disorder characterized by the replacement of the lung tissue by connective tissue, leading to progressive dyspnea, respiratory failure, or right heart failure. "Our results provide new evidence that supports the pathogenic role of IL-31RA-driven signaling in bleomycin-induced pulmonary fibrosis." (PMID 33815402, 2021). "The total lung RNA-seq analysis also suggests altered expression of several epithelial cell-associated genes with the loss of IL-31RA during bleomycin-induced pulmonary fibrosis." (PMID 33815402, 2021). "The role of IL-31RA has been investigated in other disease models, including pulmonary fibrosis and systemic sclerosis." (PMID 38081868, 2023). "In this study, we have demonstrated that bleomycin-induced pulmonary fibrosis is dependent on IL-31RA-driven signaling." (PMID 33815402, 2021). "Our previous work has depicted the effector mechanism of IL-4/IL-13 signaling in the pathogenesis of pulmonary fibrosis and the upregulation of IL-31RA via the IL-4Rα/STAT6 signaling axis." (PMID 33815402, 2021). "In addition, whole lung transcriptome analysis revealed a decrease in the expression of ECM-related genes, which thus supports the role of IL-31/IL-31RA in lung fibrosis." (PMID 33815402, 2021). "Similarly, genes associated with ECM production and remodeling were significantly decreased with the loss of IL-31RA; these genes included MMP13 and TIMP1, as well as IL-6 which increased in wildtype mice during bleomycin-induced pulmonary fibrosis." (PMID 33815402, 2021). "Therefore, potent induction of the skin and lung fibrosis by rmIL-31 in BLM-SSc mice may be attributed to the abundant expression of IL-31RA in these tissues." (PMID 34642338, 2021).
allergic disease (2 papers, 2014 to 2020). An immune response that occurs following re-exposure to an innocuous antigen, and that requires the presence of existing antibodies against that antigen. "IL-31 receptor IL-31RA, oncostatin M receptor, and IL-33 receptor ST2/IL1RL1 are also related with the immunopathological mechanisms of allergic diseases." (PMID 25061262, 2014).
asthma (2 papers, 2019 to 2023). "Although IL-31 has been implicated in asthma, the exact contribution of the IL-31 receptor (IL-31RA) signalling to airway hyperresponsiveness remains unexplored." (PMID 38081868, 2023). "To determine whether IL-31RA-induced AHR is regulated by asthma-associated gene networks, we measured the expression of Th1 and Th2 cytokines." (PMID 38081868, 2023). "Considering the contractile effects of IL-31RA in SMC isolated from multiple organs, identifying inhibitors that can mitigate IL-31RA-driven effects in SMC will have a therapeutic value beyond asthma." (PMID 38081868, 2023). "Our results from an asthma model using IL-31RA KO mice showed that IL-31R signaling negatively regulates inflammation through suppressing the proliferation of CD4+ T cells, which led to the decreased production of Th2-type cytokines." (PMID 30647024, 2019). "To determine whether increased IL-31RA expression detected in the mouse model of asthma is a feature of human asthma we assessed IL-31RA lung sections from asthmatics and healthy controls (n = 8/group)." (PMID 38081868, 2023). "Using IL-31RA as a biomarker or its correlation to asthma severity need to be further investigated." (PMID 38081868, 2023). "Consistent with dominant role for IL-31RA but not IL-31 in asthma pathogenesis in these models, IL-31RA was elevated in wildtype mice exposed to allergens and in human lung tissues obtained from asthmatics." (PMID 38081868, 2023). "To determine whether IL-13-induced AHR is IL-31RA dependent, we treated both wild-type and IL-31RA-/- mice with IL-13 and assessed AHR and other pathological and molecular changes that are relevant to asthma." (PMID 38081868, 2023).
coronavirus disease 2019 (2 papers, 2022 to 2024). "Other potential mechanisms of the RC decoction against the ALI involved the pathways of ribosome and coronavirus disease 2019 (COVID-19); the target genes of inflammatory factors, such as Ccl17, Cxcl17, Cd163, Cxcr5, and Il31ra, and lncRNAs; and the regulations of the respiratory cilia." (PMID 36072401, 2022).
fibrosis (2 papers, 2021). the formation of excess fibrous connective tissue in an organ or tissue in a reparative or reactive process. "Collectively, both IL-31 and IL-31RA expression was up-regulated in SSc DFs, suggesting a role of the IL-31/IL-31RA axis in SSc fibrosis." (PMID 34642338, 2021).